SYNPO2 (synaptopodin 2)
Description:
Has an actin-binding and actin-bundling activity. Can induce the formation of F-actin networks in an isoform-specific manner. At the sarcomeric Z lines is proposed to act as adapter protein that links nascent myofibers to the sarcolemma via ZYX and may play a role in early assembly and stabilization of the Z lines. Involved in autophagosome formation. May play a role in chaperone-assisted selective autophagy (CASA) involved in Z lines maintenance in striated muscle under mechanical tension; may link the client-processing CASA chaperone machinery to a membrane-tethering and fusion complex providing autophagosome membranes (By similarity). Involved in regulation of cell migration. May be a tumor suppressor. [Isoform 1]: Involved in regulation of cell migration. Can induce formation of thick, irregular actin bundles in the cell body. [Isoform 2]: Involved in regulation of cell migration. Can induce long, well-organized actin bundles frequently orientated in parallel along the long axis of the cell showing characteristics of contractile ventral stress fibers. [Isoform 3]: Involved in regulation of cell migration. Can induce an amorphous actin meshwork throughout the cell body containing a mixture of long and short, randomly organized thick and thin actin bundles. [Isoform 4]: Can induce long, well-organized actin bundles frequently orientated in parallel along the long axis of the cell showing characteristics of contractile ventral stress fibers. [Isoform 5]: Involved in regulation of cell migration in part dependent on the Rho-ROCK cascade; can promote formation of nascent focal adhesions, actin bundles at the leading cell edge and lamellipodia. Can induce formation of thick, irregular actin bundles in the cell body; the induced actin network is associated with enhanced cell migration in vitro.
Synonyms: MYOPODIN
Tractability: PROTAC: ubiquitination databases record sites on it.
Gene: Protein-coding gene on chromosome 4 (118,850,688 to 119,061,247, forward strand). Ensembl gene ENSG00000172403.
Subcellular location: Nucleus; Cytoplasm; Cytoplasm, cytoskeleton; Cytoplasm, myofibril, sarcomere, Z line; Cell junction, focal adhesion; Cytoplasm, cytoskeleton (Isoform 1); Cytoplasm, cytoskeleton (Isoform 2); Cytoplasm, cytoskeleton (Isoform 3); Cytoplasm, cytoskeleton (Isoform 4); Cytoplasm, cytoskeleton (Isoform 5)
Subcellular location (Human Protein Atlas): Actin filaments; Vesicles
Gene Ontology:
Molecular function: alpha-actinin binding; filamin binding; protein binding; 14-3-3 protein binding; actin binding; muscle alpha-actinin binding
Biological process: positive regulation of actin filament bundle assembly
Cellular component: actin cytoskeleton; focal adhesion; stress fiber; Z disc; nucleus; cytoplasm; cytoskeleton
Genetic constraint (gnomAD): Loss-of-function variants: 53 observed, 87.19 expected, observed/expected ratio (o/e) 0.61, 90% interval 0.49 to 0.76. The upper end of that interval is the gene's LOEUF score, 0.76, which puts it in group 3 of 6, group 1 being the genes least tolerant of losing a copy. Missense variants: 1,499 observed, 1,545.7 expected, observed/expected ratio (o/e) 0.97, 90% interval 0.93 to 1.01. Synonymous variants: 576 observed, 596.29 expected, observed/expected ratio (o/e) 0.97, 90% interval 0.9 to 1.03.
Homologues: Orthologues: macaque SYNPO2 (97% identical), chimpanzee SYNPO2 (95% identical), pig SYNPO2 (88% identical), rabbit SYNPO2 (86% identical), guinea pig SYNPO2 (83% identical), dog SYNPO2 (81% identical), mouse Synpo2 (79% identical), rat Synpo2 (73% identical), zebrafish synpo2b (17% identical), Drosophila melanogaster CG1674 (12% identical). Paralogues in human: SYNPO2L (24% identical), SYNPO (15% identical).
Diseases named in the same sentence as SYNPO2 in open-access papers:
SYNPO2 is named in the same sentence as 51 diseases in open-access papers, as found by Europe PMC text mining. Sharing a sentence is not in itself a finding about the gene and the disease. The quoted sentences say what the papers report.
prostate carcinoma (5 papers, 2015 to 2024). A carcinoma that arises from epithelial cells of the prostate gland. "Because of published data indicating that deletions in the SYNPO2 gene were associated with invasive prostate cancer, we aimed at revealing the specific localization of SYNPO2 in the normal human prostate." (PMID 38201288, 2023). "Analysis of invasive versus indolent prostate cancer tissues revealed Synpo2 expression, which is predominant in prostate acinar epithelial and basal cells, was dramatically reduced in >92% of invasive prostate cancer tissues, and loss of Synpo2 expression correlates with prostate cancer relapse." (PMID 25883213, 2015). "For example, the ILK-dependent kinase activated by Integrins α7 can phosphorylate SYNPO2 to inhibit prostate cancer proliferation and migration both in vivo and in vitro." (PMID 37544991, 2023). "Together, these results indicate SF formation is a consequence of Synpo2 effects on actin dynamics and membrane protrusion at the cell periphery, with the latter events contributing to enhanced prostate cancer cell migration in response to serum stimulation." (PMID 25883213, 2015). "Inhibiting Synpo2-induced SF assembly also prevents Synpo2-enhanced prostate cancer cell migration in response to serum-stimulation, indicating a direct correlation between SF assembly and a Synpo2 pro-migratory phenotype." (PMID 25883213, 2015). "The majority of studies on Synpo2 in the context of invasive cancer cell migration use PC3 prostate cancer cells and ectopic expression of the Synpo2As isoform, a 698-residue isoform also referred to as ΔN-MYO1." (PMID 25883213, 2015). "In prostate cancers, SYNPO2 exhibits dual functions in regulating tumor progression, with some reports showing that its C terminal region inhibits cancer invasion and metastasis while others support the notion that some isoforms of SYNPO2 increase chemokinetic properties and promotes migration." (PMID 37544991, 2023). "However, the relationship between cell migration responses and Synpo2 effects on actin or FA dynamics in prostate cancer cells are unclear." (PMID 25883213, 2015). "Similar interactions between Synpo2 and α-actinin, or with other actin regulatory proteins, might well be functionally relevant to Synpo2 effects on prostate cancer cell migration." (PMID 25883213, 2015). "Interestingly, both HOP and SYNPO2 have been implicated as tumor suppressor genes, HOP in female choriocarcinomas associated with hydatiform moles and esophageal tumors, and SYNPO2 in bladder and prostate cancer." (PMID 26624623, 2015). "Two genes (SYNPO2, PCYT1A) act in the Pi3K/Akt/mTOR pathway, involved in carcinogenesis of many tumours including colorectal-, gastric- and prostate cancer." (PMID 39543761, 2024). "In prostate cancer PC3 cells, GFP-tagged SYNPO2 truncation M56-P432 is strongly localized in the nucleus, while GFP-tagged SYNPO2 truncation M219-E758 is primarily distributed in the cytoplasm." (PMID 37544991, 2023). "The absence of NES increased SYNPO2 nuclear localization to inhibit the invasion of prostate cancer cells." (PMID 37544991, 2023). "Synaptopodin-2 (Synpo2), an actin-binding protein and invasive cancer biomarker, induces formation of complex stress fiber networks in the cell body and promotes PC3 prostate cancer cell migration in response to serum stimulation." (PMID 25883213, 2015). "Several studies, based on ectopic expression of Synpo2 in prostate cancer PC3 cells, an invasive cell type with very low levels of Synpo2 protein expression due to a hemizygous deletion, indicate Synpo2 suppresses cell invasion in vitro, and inhibits tumor development and metastasis in vivo." (PMID 25883213, 2015). "A new SYNPO2 transcript lacking the N terminus was found to promote prostate cancer cell invasion by activating RHO-ROCK signaling, indicating that abnormal SYNPO2 can initiate YAP1 nuclear translocation as well as transcriptional activity and promote cancer progression." (PMID 37544991, 2023).
breast cancer (4 papers, 2009 to 2023). A primary or metastatic malignant neoplasm involving the breast. "Studies have shown that breast cancer has a reduced amount of SYNPO2, which is associated with higher TNBC metastasis and lower patient survival." (PMID 31817810, 2019). "In breast cancer, synaptopodin-2 and caveolin-1 have been shown to modulate Akt/mTOR-regulated metastatic progression." (PMID 32615541, 2020). "Moreover, low SYNPO2 expression has been detected in bladder cancer, breast cancer, melanoma and kidney cancer." (PMID 37544991, 2023). "By reviewing the known genes involved in breast cancer metastasis and our available MDA-MB-231 cell RNA-seq data, we identified synaptopodin 2 (SYNPO2), with a known function in metastasis, which showed the highest fold change (2.05-fold increase) in MDA-MB-231 cells after vitamin C treatment." (PMID 31817810, 2019).
gastric cancer (4 papers, 2023 to 2025). A primary or metastatic malignant neoplasm involving the stomach. "The results of immunohistochemistry suggest that SYNPO2‐positive expression in tumour cells, fibroblasts, inflammatory cell may be associated with promoting peritoneal metastasis in gastric cancer." (PMID 37605453, 2023). "Through immunohistochemistry, we found that SYNPO2 is mainly expressed in the tumour cells, fibroblasts, inflammatory cell (eosinophils and lymphocytes) in gastric cancer tissue." (PMID 37605453, 2023). "Additionally, SYNPO2 expression in gastric cancer tissue with peritoneal metastasis is significantly higher than that without peritoneal metastasis." (PMID 37605453, 2023). "Quantitative polymerase chain reaction (qPCR) was used to examine the expression levels of SYNPO2, NR3C2, and CCL28 in a total of 24 gastric cancer samples and 24 margin samples." (PMID 38081950, 2023). "NR3C2, SYNPO2, and CCL28, three genes targeted by mir-21, were shown to be highly expressed in both stomach cancer and healthy tissues." (PMID 38081950, 2023). "The examination of quantitative polymerase chain reaction (qPCR) data demonstrated a substantial downregulation (p value < 0.0001) in the expression of SYNPO2, NR3C2, and CCL28 in gastric cancer tissue samples when compared to matched tumour margin samples." (PMID 38081950, 2023). "constructed gastric cancer peritoneal metastases signatures (GCPMs) through the GSE62254 database and found that the key gene SYNPO2 could be used as a prognostic marker for GCPM." (PMID 40519309, 2025).
asthma (3 papers, 2013 to 2023). "Among these, SYNPO2 gene overexpression was previously associated with reduced airway hyperresponsiveness in individuals with asthma after oral corticoid therapy." (PMID 37761964, 2023). "The other two polymorphisms identified, rs745975778 and rs61529635, were reported for the same gene, synaptopodin 2 (SYNPO2), that was reported to be associated with total serum IgE in asthmatics in an independent GWAS, suggesting roles for this gene in asthma." (PMID 33628342, 2021). "For instance, novel IgE-related genes (CRIM1, ZNF71, TLN1, and SYNPO2) were uncovered by the only GWAS of IgE in asthma patients." (PMID 37761964, 2023). "Instead, this study identified additional candidate genes (CRIM1, ZNF71, TLN1, SYNPO2, etc.)for total serum IgE levels in asthma patients." (PMID 23967269, 2013).
colorectal cancer (3 papers, 2023 to 2024). A primary or metastatic malignant neoplasm that affects the colon or rectum. "Recent studies have linked SYNPO2 gene SNPs to the progression of epithelial ovarian cancer (EOC) and the risk of familial colorectal cancer." (PMID 37544991, 2023). "Synaptopodin-2 and the Isoform 2 of Drebrin-like protein are actin-binding proteins known to be respectively invasive cancer biomarkers and potential markers for breast, lung, and colorectal cancers." (PMID 37775701, 2023). "It has been established that in colorectal cancer (CRC), SYNPO2 expression is significantly lower compared to adjacent tissues." (PMID 37544991, 2023). "In the colorectal cancer cell lines LOVO and HT29, the overexpression of SYNPO2 under hypoxic conditions was found to result in the suppression of YAP1, KLF5, and HIF-1α expression." (PMID 37544991, 2023).
bladder cancer (2 papers, 2015 to 2023). "Loss of Synpo2 expression due to methylation-dependent epigenetic silencing of gene expression is also associated with invasive bladder cancer, suggesting Synpo2 is a repressor of tumor cell invasion." (PMID 25883213, 2015). "Similarly, in a separate cohort study involving bladder cancer, around 68.7% of SYNPO2 genes in 466 tumor samples showed hypermethylation, and the methylation levels of SYNPO2 were significantly associated with tumor stage and grade." (PMID 37544991, 2023). "Moreover, SYNPO2 gene methylation was identified in 164 urine specimens from bladder cancer patients, with a specificity of 79.8% and an accuracy of 75.3% compared to controls." (PMID 37544991, 2023).
cardiomyopathy (2 papers, 2023 to 2025). A disease of the heart muscle or myocardium proper. "While we did not identify SYNPO2 mutations in its IDR that are attributed to cardiomyopathy, it has been reported that the reduced expression of SYNPO2 destabilizes myofibrils." (PMID 36628457, 2023). "Transgenic expression of P209L BAG3 in the mouse heart induced protein aggregates, with sequestration of endogenous WT BAG3 as well as sarcomere-associated proteins such as desmin, α-actinin, and myopodin (SYNPO-2) in aggregates, provoking sarcomere disruption and cardiomyopathy." (PMID 39932799, 2025).
Epithelial Ovarian Cancer (2 papers, 2018 to 2024). "The METTL14 loci carried synaptopodin 2 (SYNPO2), where a mutation looped between the first intron of this gene and the METTL14 promotor was linked to increased susceptibility to ovarian cancers in humans." (PMID 39596561, 2024).
melanoma (2 papers, 2022 to 2023). A malignant, usually aggressive tumor composed of atypical, neoplastic melanocytes. "As expected, SYNPO2, whose promotor methylation and low transcriptional expression were found to associate with metastasis and poor clinical outcome in melanoma, can be a potential predictor to provide new therapeutic strategies in this study." (PMID 35479936, 2022). "A six-gene panel, including SYNPO2, has been identified for predicting the response of melanoma to anti-PD-1 therapy." (PMID 37544991, 2023). "Using WGCNA combined with supervised machine learning algorithms, we identified a novel CAFs-related panel, including six genes (CDK14, SYNPO2, TCF4, GJA1, CPXM1, TFPI), which can distinguish the response of melanoma patients under anti-PD-1 immunotherapy." (PMID 35479936, 2022).
neuroblastoma (2 papers, 2012 to 2023). Neuroblastoma (NB) is the most common solid, extracranial childhood tumor. "Conversely, a transcriptomic study on neuroblastoma SK-N-SH cells revealed that SARS-CoV-2 infection induced a downregulation of several members of building blocks of the cytoskeleton, as well as some of their regulators (i.e., TUBA1A, TUBA4A, TUBB4A, STMN4, TMSB15A, SYNPO2)." (PMID 37896797, 2023).
triple-negative breast carcinoma (2 papers, 2019 to 2020). An invasive breast carcinoma which is negative for expression of estrogen receptor (ER), progesterone receptor (PR), and human epidermal growth factor receptor 2 (HER2). "Synaptopodin-2 (SYNPO2) inhibited YAP/TAZ to suppress triple-negative breast cancer (TNBC) metastasis." (PMID 31893023, 2019).
atherosclerosis (1 paper, 2024). A disease characterized by the build-up of fatty material and calcium deposition in the arterial wall resulting in partial or complete occlusion of the arterial lumen. "SYNPO2 downregulation is associated with atherosclerosis and may contribute to the vascular anomalies and stenosis seen in this disorder." (PMID 39480826, 2024).
autosomal dominant cutis laxa (1 paper, 2024). Autosomal dominant cutis laxa (ADCL) is a connective tissue disorder characterized by wrinkled, redundant and sagging inelastic skin associated in some cases with internal organ involvement. "MYH11 and SYNPO2 linked to EMILIN1-related Connective Tissue Disease, AOC3 and MYH11 linked to Autosomal Dominant Cutis Laxa, MYH11 and SYNPO2 linked to Lethal Arteriopathy Syndrome due to Fibulin-4 Deficiency, while AOC3 and TAGLN linked to Renal Tubular Dysgenesis of Genetic Origin." (PMID 39480826, 2024).
Cognitive impairment (1 paper, 2025). Abnormal cognition is characterized by deficits in thinking, reasoning, or remembering. "Moreover, SYNPO2 overexpression exacerbated neuroautophagy despite BMSC treatment, while SYNPO2 depletion notably reduced neuroautophagic damage and alleviated cognitive impairments, retaining the neuroprotective efficacy of BMSC treatment." (PMID 40000609, 2025).
colon cancer (1 paper, 2023). "In this regard, genomic methylation levels of SYNPO2 in colon cancer were found to be negatively correlated with its protein expression, and low SYNPO2 expression exhibited a positive correlation with advanced stage and poor survival." (PMID 37544991, 2023).
cryptorchidism (1 paper, 2025). The failure of one or both testes of a male fetus to descend from the abdomen into the scrotum during the late part of pregnancy. "The results showed that six target proteins of TJP2, ZO-1, SYNPO2, SYNPO, LMCD1, and MCU showed characteristic distribution in the epididymal tissues of the cryptorchidism group and the normal control group." (PMID 41217791, 2025).
cutis laxa (1 paper, 2024). Cutis laxa (CL) is an inherited or acquired connective tissue disorder characterized by wrinkled, redundant and sagging inelastic skin associated with skeletal and developmental anomalies and, in some cases, with severe systemic involvement. "A literature search returned no explicit connection between SYNPO2 (Synaptopodin 2) and Cutis Laxa or Lethal Arteriopathy Syndrome due to Fibulin-4 Deficiency." (PMID 39480826, 2024).
depression (1 paper, 2021). "For interaction analysis, we detected that OLFM1 interacted with champagne/white wine in depression, while SYNPO2 interacted with coffee type in fluid intelligence." (PMID 33807197, 2021).
Duchenne muscular dystrophy (1 paper, 2023). Duchenne muscular dystrophy (DMD) is a neuromuscular disease characterized by rapidly progressive muscle weakness and wasting due to degeneration of skeletal, smooth and cardiac muscle. "SYNPO2 is also known as genethonin-2, the product of a gene that was found to be downregulated in patients with Duchenne muscular dystrophy (DMD) or as myopodin." (PMID 38201288, 2023).
hepatocellular carcinoma (1 paper, 2023). A malignant tumor that arises from hepatocytes. "A higher ratio of cytoplasmic to nuclear SYNPO2 in patients with hepatocellular carcinoma (HCC) has been linked to an increased likelihood of recurrence, and CaN-induced nuclear-cytoplasmic shuttling of SYNPO2, facilitating the metastasis of HCC by promoting the assembly of peripheral actin bundles." (PMID 37544991, 2023).
Hernia (1 paper, 2021). "The microtubule associated protein 1 light chain 3 γ (MAP1LC3C), vitrin (VIT), aggrecan (ACAN), alkaline ceramidase 2 (ACER2), potassium calcium-activated channel subfamily M α 1 (KCNMA1) and synaptopodin 2 (SYNPO2) genes are highlighted as candidates to trigger both types of hernia." (PMID 33513662, 2021).
kidney tumor (1 paper, 2023). "In a cohort study involving 88 kidney tumor samples, 50 cases (56.8%) revealed an association between the methylation status of the SYNPO2 and the Memorial Sloan-Kettering Cancer Center (MSKCC) risk score and distant metastasis." (PMID 37544991, 2023).
lung carcinoma (1 paper, 2018). "On the other hand, SYNPO2, ADH1B and INMT were found to be repressed in HIV-associated lung cancer." (PMID 30177858, 2018). "Also, 11 of 14 (78.6%) tumors had decreased SYNPO2 mRNA (13.26-fold) in HIV lung cancer, except SYNPO2 was undetectable in 3 pairs of lung cancer and adjacent non-cancer tissue samples." (PMID 30177858, 2018). "We also found decreased ADH1B, INMT and SYNPO2 mRNA levels in HIV lung cancer." (PMID 30177858, 2018).